IFNB1 (interferon beta 1)
Description:
Type I interferon cytokine that plays a key role in the innate immune response to infection, developing tumors and other inflammatory stimuli. Signals via binding to high-affinity (IFNAR2) and low-affinity (IFNAR1) heterodimeric receptor, activating the canonical Jak-STAT signaling pathway resulting in transcriptional activation or repression of interferon-regulated genes that encode the effectors of the interferon response, such as antiviral proteins, regulators of cell proliferation and differentiation, and immunoregulatory proteins. Signals mostly via binding to a IFNAR1-IFNAR2 heterodimeric receptor, but can also function with IFNAR1 alone and independently of Jak-STAT pathways (By similarity). Elicits a wide variety of responses, including antiviral and antibacterial activities, and can regulate the development of B-cells, myelopoiesis and lipopolysaccharide (LPS)- inducible production of tumor necrosis factor (By similarity). Plays a role in neuronal homeostasis by regulating dopamine turnover and protecting dopaminergic neurons: acts by promoting neuronal autophagy and alpha-synuclein clearance, thereby preventing dopaminergic neuron loss (By similarity). IFNB1 is more potent than interferon-alpha (IFN-alpha) in inducing the apoptotic and antiproliferative pathways required for control of tumor cell growth (By similarity).
Synonyms: IFN-beta; IFB; IFNB; IFF
Tractability: Small molecule: a structure with a bound ligand is known; it has a binding pocket of medium quality. Antibody: a drug acting on it is in phase 2 or 3 trials; UniProt places it where antibodies can reach, with high confidence; its Gene Ontology location is reachable by antibodies, with high confidence; UniProt predicts a signal peptide or a membrane-spanning region.
Target class: Secreted protein
Gene: Protein-coding gene on chromosome 9 (21,077,104 to 21,077,942, reverse strand). Ensembl gene ENSG00000171855.
Subcellular location: Secreted
Pathways (Reactome):
Immune System: Interferon alpha/beta signaling; Regulation of IFNA/IFNB signaling; TRAF3-dependent IRF activation pathway; TRAF6 mediated IRF7 activation
Disease: Evasion by RSV of host interferon responses; SARS-CoV-2 activates/modulates innate and adaptive immune responses
Cellular responses to stimuli: Oxidative Stress Induced Senescence
Hemostasis: Factors involved in megakaryocyte development and platelet production
Gene Ontology:
Molecular function: chloramphenicol O-acetyltransferase activity; cytokine activity; cytokine receptor binding; protein binding; type I interferon receptor binding
Biological process: B cell activation involved in immune response; cell surface receptor signaling pathway via JAK-STAT; cell surface receptor signaling pathway via STAT; cellular response to interferon-beta; cellular response to virus; cytokine-mediated signaling pathway; innate immune response; negative regulation of T cell differentiation; negative regulation of T-helper 2 cell cytokine production; negative regulation of viral genome replication; positive regulation of apoptotic signaling pathway; positive regulation of transcription by RNA polymerase II; response to exogenous dsRNA; type I interferon-mediated signaling pathway; adaptive immune response; B cell proliferation; cell surface receptor signaling pathway; cellular response to exogenous dsRNA; defense response to virus; humoral immune response; natural killer cell activation; natural killer cell activation involved in immune response; negative regulation of Lewy body formation; neuron cellular homeostasis; positive regulation of autophagy; and 12 more
Cellular component: extracellular region
Genetic constraint (gnomAD): Missense variants: 261 observed, 215.01 expected, observed/expected ratio (o/e) 1.21, 90% interval 1.1 to 1.35. Synonymous variants: 95 observed, 83.06 expected, observed/expected ratio (o/e) 1.14, 90% interval 0.97 to 1.36.
Homologues: Orthologues: chimpanzee IFNB1 (97% identical), macaque IFNB1 (95% identical), pig IFNB1 (65% identical), dog IFNB1 (60% identical), rabbit IFNB1 (56% identical), guinea pig IF1DA1 (54% identical), guinea pig IF1DA2 (52% identical), mouse Ifnb1 (48% identical), rat Ifnb1 (48% identical), zebrafish ifnphi3 (25% identical), zebrafish ifnphi2 (22% identical), tropical clawed frog ifn4 (18% identical). Paralogues in human: IFNA2 (36% identical), IFNE (34% identical), IFNW1 (34% identical), IFNA14 (33% identical), IFNA16 (33% identical), IFNA4 (33% identical), IFNA6 (33% identical), IFNA10 (33% identical), IFNA13 (33% identical), IFNA17 (33% identical), IFNA7 (33% identical), IFNA8 (33% identical), and 4 more.
Diseases named in the same sentence as IFNB1 in open-access papers:
IFNB1 is named in the same sentence as 510 diseases in open-access papers, as found by Europe PMC text mining. Sharing a sentence is not in itself a finding about the gene and the disease. The quoted sentences say what the papers report.
viral infection (1,017 papers, 2005 to 2026). "Interferon-β (IFN-β) is a protein encoded by the IFNB1 gene that belongs to the type I class of IFNs; it is involved in pathogens response, especially in fighting viral infections." (PMID 38263055, 2024). "Upregulation of INFα/β is canonically associated with bacterial or viral infections, during which foreign DNA or RNA is recognized by specific pattern-recognition receptors, leading to upregulation of IFNB1 transcription." (PMID 36107856, 2023). "Accordingly, virus infection causes higher expression of IFNa2, IFNb1, OAS1, and STAT2 in Nlrx1−/− mice when compared to wild-type mice." (PMID 33525590, 2021). "The depletion of SNRNP200 in human cells resulted in a reduced interferon-β (IFNB1) production and increased susceptibility to viral infection." (PMID 27454487, 2016). "Following virus infection, expression of IFN-β (measured by enzyme-linked immunosorbent assay [ELISA]) and the mRNA level of the IFN-stimulated gene 56 (ISG56, measured by RT-qPCR) were increased approximately twofold as compared to WT cells without a detectable change in Ifnb1 mRNA levels." (PMID 35878012, 2022). "In our study, we found that the transcription of IFNB1 was significantly impaired in ORMDL3-overexpressing cells in response to viral infection." (PMID 40126553, 2025). "Although the absolute read count is modest, this finding is consistent with prior studies reporting low but inducible IFNB1 expression in epithelial cells upon viral infection." (PMID 41267684, 2025). "Next, we compared the top 10 upregulated cytokines/chemokines and found strong upregulation of IFNL2/3, IL-6, and IFNB1 in all animals with severe yellow fever." (PMID 40663406, 2025). "Histone modifications have been shown to contribute to the tight regulation of the IFNB1 promoter during virus infection." (PMID 38399974, 2024). "Whereas interferon beta 1 (IFNB1)-based antiviral therapies are generally effective to treat viral infections, ZBP1-triggered inflammatory cell death limits the therapeutic efficacy of IFNB1 during coronavirus infection." (PMID 38932258, 2024). "After viral infection, the hyperacetylation of H3 and H4, which is correlated with active chromatin, was found in the promoter and 5′ end of the IFNB1 gene." (PMID 38399974, 2024). "To better understand the response of microglia after virus infection, we investigated the IFNB1, IFNA1, and IFNA5 expression at the MOIs 0.1, 0.01, and 0.001, where the viability was near 50% after infections at 3 DPI." (PMID 38213031, 2024). "IFIT1 and IFNB1 expression was induced by viral infection, and we found that the fraction of cells expressing IFIT1 was higher than the fraction expressing IFNB1 at multiple timepoints in infection." (PMID 37814072, 2023). "The induction of the cytokine interferon beta 1 (Infb1) is part of the first line of defense against viral infection in the host cell." (PMID 34146543, 2021). "IFNB1 expression is often utilized as a readout for innate immune activation during viral infections." (PMID 35118008, 2021). "The transcription of the IFN-β coding gene, IFNB1, is rapidly induced upon viral infection through multiple pathways sensing virus-derived nucleic acids." (PMID 33147208, 2020). "While expression of Ifnb1 and Cxcl10 was increased in peritoneal exudate cells 12 hr after virus infection in WT mice, such response was diminished in Stinggt/gt mice." (PMID 32886065, 2020). "As expected, pro-inflammatory genes (e.g., Ifnb1, MCP-1/Ccl2, Cxcl10) associated with a response to viral infection were most prominently upregulated in H3N2 and H5N1 infected mice, as evident in gene ontology (GO) analyses." (PMID 32231671, 2020). "Viral infection is recognized by infected cells, triggering the IFN-β pathway, which leads to the transcriptional expresion of the IFNB1 gene as well as other genes." (PMID 32365702, 2020).
viral infection (continued). "Phosphorylation of the constitutively expressed transcription factor IRF3 early in the cellular response to viral infection is a key event in the initial transcriptional activation of the mouse Ifna4 and Ifnb1 genes." (PMID 31076606, 2019). "For example, IRF3 forms a complex with CREB binding protein (CBP)/p300 histone acetyltransferase (HAT) through the IAD1 domain for the induction of Ifnb1 transcription in response to virus infection." (PMID 30671058, 2018). "The knockdown of cGAS or STING completely abrogated IFNβ release and Ifnβ1 and Mx1 gene expression induced by viral infection or 8GyX3 treatment of TSA cells in vitro." (PMID 28598415, 2017). "Because IFNB1 expression is induced by virus infection, each of these experiments was performed in both uninfected and SeV-infected IMR90 primary human fibroblast cells." (PMID 25348400, 2014). "Consistently, knockdown of RNF26 inhibited the expression of IFNB1 gene in various cells at the early phase and promoted it at the late phase of viral infection, respectively." (PMID 25254379, 2014). "Here we show that secretion of WNT2B and WNT9B and stabilization of β-catenin (CTNNB1) upon virus infection negatively regulate expression of representative inducible genes IFNB1, IFIT1 and TNF in a CTNNB1-dependent effector mechanism." (PMID 23785285, 2013). "Overall, these results strongly support a specific effector role of virus-induced secretion of WNT2B and WNT9B ligands in innate immunity, acting in a feedback inhibition of IRF3- and NF-κB-dependent IFNB1 response to virus infection." (PMID 23785285, 2013). "WNT2B and WNT9B secretion in response to viral infection induce a CTNNB1-dependent signaling pathway leading to decreased magnitude of IFNB1 production and effector response in a feedback inhibition mechanism." (PMID 23785285, 2013). "What is the source of the low level of IFNB1 detected at early time points after virus infection that is necessary to initiate the positive feedback loop and generate a full antiviral response?" (PMID 21347441, 2011). "Next, we characterized whether the cells expressed interferon β1 (IFNB1) or the interferon stimulated gene (ISG) MX1 in response to treatment with IFN or virus infection." (PMID 38743751, 2024). "To test whether ORF3c is able to suppress immune activation upon viral infection, we monitored endogenous IFNB1 expression upon infection with Sendai virus (SeV), a potent inducer of RIG‐I‐mediated type I IFN expression." (PMID 37870297, 2023). "Furthermore, viral infection increased the mRNA expression of cytokines (Il6, Tnf), chemokines (Cxcl10, Ccl2), and interferon-responsive genes (Ifnb1, Ifit3, Irf7, Gbp5 and Isg15)." (PMID 37081549, 2023). "Notably, IFN-Is, and particularly IFNB1, are already approved for use in the treatment of certain viral infections (hepatitis B and hepatitis C), with their administration in the early infection stages being the key for their effectiveness." (PMID 38077337, 2023). "Similarly, the deletion of METTL3 or YTHDF2 has been reported to stabilize IFNB1 in an m6A-dependent manner following viral infection, leading to subsequent suppression of the virus reproduction in host cell." (PMID 35120571, 2022). "In that context, virus infection readily induces the transcription of the Ifnb1 and Ifna4 genes." (PMID 34015056, 2021). "IFNB1 is a well-studied cytokine that is released in response to a viral infection." (PMID 34960686, 2021). "Furthermore, while certain genes were repressed during both virus infections (e.g., Irf7 or Ifnb1), expression of others was more prominently reduced upon H5N1 infection (e.g., IL-1β, IL-6, Ccl2)." (PMID 32231671, 2020). "The A549 human lung adenocarcinoma cell line, which is known to elicit a robust type I interferon response to virus infection with rapid upregulation of the IFNB1 gene and thus serves as a positive control, responded to MRBV infection with a robust increase in IFNB1 expression." (PMID 28854921, 2017).
viral infection (continued). "These genes acting either as positive or negative regulators upon silencing provide a functional validation of our RNAi data and identify novel regulators of IFNB1 expression required to control virus infection and to prevent excessive activation in autoimmune diseases." (PMID 23785285, 2013). "Furthermore, although levels of interferon protein secretion were undetectable in most cultures, viral infection consistently upregulated IFNB1 and IL28 mRNA, and these responses were also lower in the asthma group." (PMID 24219422, 2013). "Meanwhile, the upregulation of interferon beta 1 (Ifnb1) and IAV M mRNA expression was used as a confirmation of active viral infection." (PMID 38940585, 2024). "Meanwhile, the upregulation of interferon beta 1 (Ifnb1) and IAV M mRNA expression was used to confirm active viral infection." (PMID 39334466, 2024). "IFIT1 transcription is strongly induced during virus infection and induction of IFIT1 expression can be detected well before IFNB1 expression." (PMID 37814072, 2023). "In the present study, we determined that viral infection markedly induced the interaction of TOB1 with IRF3, which is bound to the promoter region of Ifnb1 in macrophages." (PMID 36085336, 2022). "We found that viral infection-induced TOB1 interacted with IRF3 and bound to the promoter region of Ifnb1, leading to recruitment of HDAC8 and suppression of IFN-β production." (PMID 36085336, 2022). "In this study, we demonstrated that viral infection induced the interaction of the transducer of ERBB2.1 (TOB1) with IRF3, which bound to the promoter region of Ifnb1 in macrophages." (PMID 36085336, 2022). "Upon virus infection, BRD3 promotes the recruitment of the IRF3/p300 complex to the promoter of Ifnb1, leading to the transcription and production of type I interferon." (PMID 35743279, 2022). "Knockdown of YAP/TAZ or TEADs increased the transcriptional expression of antiviral and proinflammatory factors IFNB1, CXCL8 and IRF7 induced by virus infection." (PMID 35503798, 2022). "The remaining 20 non-targetable SARS-CoV-associated disease genes include proteins (e.g., CD14, IFNA1, IFNB1, IL4, IL10, CCL5) having key roles in the immune-inflammatory response to viral infection as well." (PMID 33544720, 2021). "Knockdown of NLRX1 leads to enhanced transcription levels of IFNb1, STAT2, and the 2′-5′-oligoadenylate synthetase 1 gene (OAS1) after viral infection, suggesting a negative regulatory role of NLRX1 on the IFN-β/STAT2/OAS1 axis." (PMID 33525590, 2021). "We selected IFNB1, IL6, and CXCL8 as markers of host response, representative of overlapping transcriptional responses to viral infection." (PMID 34357881, 2021). "SARS-CoV-2 infection of Calu-3 cells, as expected from similar results for SARS-CoV infections, led to induction of a range of genes known to respond to viral infections, such as IFIT2, OAS2, or IFNB1." (PMID 33585804, 2021). "Again, IFNB1 and OAS1 mRNA levels were lower in the mutant compared to the revertant virus infection at several time points." (PMID 32365141, 2020). "In the super-SILAC detected DEPs, consistent prediction of IFNG was computed out; in addition, other known viral infection relevant pathways, such as IFNA2, IFNB1 and TLR, were also deemed up-stream activators by IPA." (PMID 28117408, 2017). "The results suggest that SNRNP200 specifically regulates IRF3 activation upon RNA virus infection to promote IFNB1 induction and IFN effector responses, and thus demonstrates its importance in controlling viral infections." (PMID 27454487, 2016). "Concordantly, circHOMER1 dampened the transcription of IFNB1 and CXCL10 after viral infection." (PMID 40662732, 2025). "We found no expression of IFNA1 and IFNA5 (data not shown), and dose-dependent IFNB1 expression after virus infection, indicating innate immune signaling activation." (PMID 38213031, 2024).
viral infection (continued). "We next characterized whether the cells expressed interferon β (IFNB1) and the IFN-stimulated gene (ISG) MX1 in response to IFN or virus infection." (PMID 37146034, 2023). "We identified that TGFβ suppressed IFNB1 expression as well as the interferon inducible genes, MX1 and viperin, consistent with the potential for TGF-β to suppress the innate immune response to viral infection." (PMID 35977489, 2022). "Virus infection is known to trigger several activation pathways, including the RIG-I/MDA5 pathway, among which some might induce IFNB1 expression independently from FIRE, or at levels sufficient to mask the effects of rs12553564." (PMID 33147208, 2020). "In line with a primary inhibitory effect, knockout of murine p50 does not affect induction of IFNB1 expression after virus infection." (PMID 32645843, 2020). "Indeed, TRIM33 has been shown to regulate NLRP3 inflammasome activation in response to bacterial or viral infection through a direct interaction with DHX33 in the cytoplasm and to regulate Ifnb1 transcription at the late stages of BMDM activation." (PMID 27974684, 2017). "Viral infection activates a signaling cascade that culminates with the phosphorylation and subsequent nuclear translocation and DNA-binding of Interferon Response Factor 3 (IRF3), which activates IFNB1 transcription." (PMID 25348400, 2014). "Coherently, we found that viral infection induces the accumulation of an active form of CTNNB1 and that CTNNB1 gene silencing increases SeV-induced IFNB1, IFIT1 and TNF expression, as well as NFKBIA (IκBα) phosphorylation at serine 32 (P-Ser32) to release NF-κB inhibition." (PMID 23785285, 2013). "Upon viral infection of DCs, constitutive RIG-I proteins (coded from the gene DDX58) can be activated upon detecting evidence of negative stranded viruses such as NDV in the cytoplasm, leading to IFNB1 induction through a signaling cascade." (PMID 21347441, 2011). "When stimulated with Poly(I:C), there was also no expression of interferon-beta (IFNB1), a cytokine present in viral infection." (PMID 20842748, 2010). "Interestingly, this induction was observed following infection with both live and UV-inactivated virus, indicating that VPA-responsive IFNB1 transcript accumulation depends on viral infection, but not de novo viral gene expression." (PMID 38932169, 2024). "IRF3, IRF7, and IFNB1, which are upregulated naturally in response to viral infection, could not stimulate an immune response due to the activation of the P viral protein." (PMID 27872612, 2016). "MCOLN2 promoted ISG but not IFNB1 expression in response to SINV, despite having a net positive effect on viral infection." (PMID 29382735, 2018). "To test whether RUNX1 could directly regulate IFN-β signaling, we analyzed the expression of IFNB1, MxA and ISG15 in the A549 cells without viral infection." (PMID 35248104, 2022).